CD4 (CD4 molecule)
Diseases named in the same sentence as CD4 in open-access papers (continued):
Sharing a sentence is not in itself a finding about the gene and the disease.
infection (continued). "In contrast, our data with LPS pre-treated DC suggested that tetherin potently restricts DC-mediated cis-infection of CD4+ T cells." (PMID 23311681, 2013). "Others tested a model for abortive infection of CXCR4+ tonsil CD4 cells where cytoplasmic viral DNA triggered a cell death pathway." (PMID 23742646, 2013). "In contrast, in mice vaccinated with adjuvanted recombinant H28 alone (H28/H28) we observed the highest production of IL-2 per single cell and the highest frequency of antigen specific TNF-α/IL-2 expressing CD4 T cells pre and post infection." (PMID 23977248, 2013). "Direct interaction between MBL and HIV has been shown by several groups and we have recently shown that SP-A binds to HIV and inhibits infection of CD4+ cells but enhances dendritic cell-mediated viral transfer to CD4+ cells." (PMID 23527085, 2013). "The HIV enhancing effect of HD5 is observed in infection of primary activated CD4+ T cells by both R5 and X4 primary isolates when viruses are pre-incubated with defensins in the absence of serum." (PMID 24086683, 2013). "Throughout the infection there was an increased proportion of CD4+ cells expressing Foxp3 in B6.CCR7-/- mice." (PMID 24205367, 2013). "Infection starts when gp120, the viral envelope glycoprotein, binds to CD4 and to a chemokine receptor usually CCR5 or CXCR4." (PMID 24312095, 2013). "Depletion of CD4 T cells at distinct times relative to infection showed that CD4 T cells not only enhance peripheral CD8 T-cell priming/expansion, but further promote CD8 T-cell function locally within the central nervous system (CNS)." (PMID 23237504, 2012). "In the course of infection, both mouse strains increased the numbers of pulmonary CD4+CD25+Foxp3+ Treg cells." (PMID 23226464, 2012). "We show that elevated cellular susceptibility to infection is associated with high levels of T cell activation ex vivo and that HIV preferentially targets activated CD4+ T cells." (PMID 23029309, 2012). "sCD4 sensitivity, gp120/CD4-IgG binding and infection of primary macrophages of the evolving R5 viruses in the three RPs without evidence of coreceptor switch were then determined." (PMID 23237529, 2012). "Similar results were obtained upon infection of primary CD4+ T cells, even if the effect of hyperthermia was less marked (2.5 fold increase)." (PMID 22807676, 2012). "At day 2 post-infection, we observed an 84% higher proportion of IL-10-producing splenic CD4+ T cells from rD7-immunized mice compared to splenocytes of mock-immunized mice (p = 0.016)." (PMID 23236530, 2012). "An accessible sialyllactose moiety on viral membrane gangliosides is shown to be essential for HIV-1 uptake into mature dendritic cells, thereby promoting viral transfer and infection of bystander CD4+ T lymphocytes." (PMID 22545022, 2012). "JES6-1 treatment on days 0, 2 and 4 of infection partially inhibits the expansion of the CD4+CD25+Foxp3+ cell population during acute malaria." (PMID 22272258, 2012). "CD4+ T cells that survive the acute phase of infection are retained as memory cells and Mtb-specific memory CD4+ T cells are central to prevent progression to TB in healthy latently infected individuals." (PMID 22545156, 2012). "The HIV-1 envelope protein, M-gp120, which is critical for the attachment and infection of CD4+ T cells, can induce the migration of iDCs in vitro." (PMID 23119100, 2012). "These kinds of studies should be conducted in HIV-positive individuals in the chronic stage of the infection with similar CD4+ T cell count, and whose spVL have being well established." (PMID 22429506, 2012). "De Boer and Perelson study three different model types and they point out that the clinically observed patterns in disease progression cannot be explained in target-cell limited models by infection of CD4+ T-cells alone." (PMID 23202449, 2012).
infection (continued). "Guido Silvestri reviewed the similarities between HIV and pathogenic SIV infection of macaques including chronic immune activation, mucosal immune dysfunction, microbial translocation and high levels of infection of central-memory CD4+ T cells." (PMID 22853692, 2012). "In contrast to this accepted model, results presented in this study indicate that cocaine targets the post entry steps of HIV-1 life cycle since cocaine was added to the CD4+ T cells after infection." (PMID 23251514, 2012). "Tracking the Salmonella-specific CD4+ T cell response over time revealed that the most immunodominant response throughout infection was against the STM1540262–276 epitope, followed by AhpC154–168 and EutC243–257 respectively." (PMID 22912884, 2012). "At the incipient stages of HIV infection, there is a massive loss of GALT-associated CD4+ T cells in animal models of simian immunodeficiency virus (SIV) and HIV in humans as a consequence of direct infection." (PMID 22479485, 2012). "It is therefore difficult to distinguish at this early stage of infection if the low CD4+ T cell counts, or the high VL levels, are due to a particularly early diagnosis (close to the VL peak) or rather should be considered as a sign of bad prognosis." (PMID 23056251, 2012). "The mild infection was also evidenced by the moderate CD4+ T cell decline in peripheral blood (average CD4+ T cells 441/mm3)." (PMID 23150992, 2012). "Instead they recruit CD4+ T cells and contribute to the establishment of infection at sites of viral entry, i.e. the mucosal barrier." (PMID 23035819, 2012). "Infection of BALB/c mice with L. major induces early production of IL-4 by CD4+ T cells carrying the Vβ4α8 T cell receptor at 16 h after infection." (PMID 22838729, 2012). "A recent study demonstrated that cell-free HTLV-1 efficiently infects DCs, and the infected DCs promote de novo infection of CD4+ T cells." (PMID 22647666, 2012). "Using purified GFP+ Tregs, we found LmΔactA infection midgestation triggered ∼2-fold reductions in suppressive potency for maternal Tregs compared with GFP+ CD4 cells recovered from uninfected pregnant controls." (PMID 22916020, 2012). "In the course of infection, CD4+ T cells were collected and analyzed for the expression of early CD69 and late CD30 activation markers using flow cytometry." (PMID 22359669, 2012). "The most important immunologic abnormality shown in experimental as well as in natural infection is a decrease in the number and relative proportion of CD4+ cells in the peripheral blood as well as in most primary lymphoid tissues." (PMID 23202500, 2012). "HIV preferentially establishes productive infection in activated CD4+ T cells due its dependency on host substrates for viral entry and replication." (PMID 23029309, 2012). "This correlation suggests that viral load is an important factor driving SIV DNA turnover in resting CD4 T cells during active infection." (PMID 22496643, 2012). "During infection by M. tuberculosis or M. avium complex which is also a pathogenic NTM, CD4+ T cells, interferon (IFN)-γ, or IL-12p40 are crucial for the development of protective immunity in mice." (PMID 22558425, 2012). "If true, this would suggest that chimpanzee α1PI differs from human α1PI since HIV-1 infected chimpanzees survive infection and regain normal numbers of CD4+ lymphocytes." (PMID 22363634, 2012). "In the present study, we found that H681 conferred exposure of CD4bs that resulted in increased infection in HeLa cells and macrophages both expressing low cell surface CD4." (PMID 22606344, 2012). "In HIV-1 clade B infection, age at treatment initiation was a strong predictor of CD4 cell restoration in our clade C infected cohort." (PMID 22348047, 2012). "As with CD4+ T cell responses, a strong multispecific CD8+ T cell response produced early in infection is associated with viral clearance." (PMID 22754568, 2012).
infection (continued). "Infection of CD4+ target cells by HIV is a complex, multi-stage process involving viral attachment to host cells and subsequent membrane fusion." (PMID 22851920, 2012). "s is the assumed constant rate of production of CD4+ T -cells, μ is their per capita death rate, βxy is the rate of infection of CD4+ T -cells by virus, and vy is the rate of disappearance of infected cells." (PMID 22214194, 2012). "Together these data demonstrate that boosting of CD4+ T cell responses during infection with peptide-based vaccines improves the clearance and burden of virulent Salmonella bacteria." (PMID 22912884, 2012). "We found that HCV-specific T cell responses were readily detectable in approximately half the patients with chronic genotype-3a infection, with CD4 T cell subsets targeting the core protein and CD8 T cells targeting the NS HCV proteins." (PMID 22337948, 2012). "In the lung, there is evidence that the number of CD8+ cells are contracting by day 14 after infection and by day 21 CD4+, CD8+ and γδTCR+ lymphocytes had all returned to baseline numbers." (PMID 22428026, 2012). "DC-SIGN expressed by dendritic cells captures HIV-1 resulting in trans-infection of CD4+ T-lymphocytes." (PMID 22412885, 2012). "Infection with CVB3 induced a slight increase of CD4+ T cells (23±0.15% of MNCs, p = 0.04 vs. PBS-Co) in the spleen of untreated mice, which was however further potentiated by MSCs (38±4.8% of MNCs, p = 0.016 vs. PBS-CVB3)." (PMID 22815907, 2012). "Findings that suggest ongoing replication include the detection of HIV-1 RNA in lymphoid and gut tissue as well as evidence of cross-infection between cellular compartments in CD4+ T cells and GALT, despite undetectable HIV-1 RNA in plasma." (PMID 22396745, 2012). "Investigation into direct infection of resting CD4 T cells by spinoculation has resulted in postintegration latency in these spinoculated cells within 72 h in all CD4 T-cell subsets, including both naive and memory T cells." (PMID 22848825, 2012). "Expression of CCR5 and CXCR4 on CD4+ iNKTs makes them susceptible to infection with R5-tropic, X4-tropic, and primary isolate viruses, resulting in the preferential depletion of CD4+ iNKT cells during in vitro infection." (PMID 22916008, 2012). "CD4+ T cells will be activated by factors secreted from infected macrophages and either killed directly, killed by infection or subverted into CD4+ T cell reservoirs." (PMID 23035819, 2012). "The highest total numbers of CD4+CD44hiCXCR5+CD150lo cells were found in the spleen after infection, a result that once again reflects total cell yield." (PMID 22792401, 2012). "Inhibiting this mechanism stops infection by binding CD4 with gp120 and preventing CD4-induced conformational isomerization which initiates co-receptor binding and viral cell fusion." (PMID 23202307, 2012). "Multivariate analyses of other cohorts have identified higher CD4+ cell count as a predictor of R5 infection in both TN and TE patients with subtype B and C HIV-1 infections." (PMID 22281097, 2012). "Here we show varying levels of humoral immune response over infection time had little impact to HIV diversity, however reduction of CD4+ T cells counts is the main cause of the low intensity of positive selection." (PMID 22768122, 2012). "IL-27 plays a role in the development of IFNγ+IL-10+ CD4+ T cells during experimental L. major and Listeria monocytogenes infection in vivo, as assessed using IL-27Rα−/− mice." (PMID 22911108, 2012). "An effective vaccine will most likely require the induction of antigen specific CD8+ and CD4+ T-cells as well as long-lasting antibody responses all working in concert to eliminate the infection." (PMID 23144750, 2012). "CD8 T cell responses commonly targeted the non-structural (NS) proteins in chronic genotype-3a infection whereas in genotype-1 infection CD4 responses targeting HCV core predominated (p=0.0183)." (PMID 22337948, 2012).
infection (continued). "The killing of primary CD4+ T cells in the infected SupT1/PBMC cocultures started to be strong on average 7–8 days post infection, when the large majority of SupT1 cells were removed by the HIV-1 virus." (PMID 22701517, 2012). "Macrophages and DCs are important cell types in the pathogenesis of SIV and HIV because they are early targets for infection and long-lived virus-producing cells capable of promoting viral transfer to CD4+ T cells." (PMID 23344558, 2012). "As the infection progresses, first splenic CD4+ cells are the predominate IFN-γ+ cells (day 14) only to be usurped by CD8+ cells at day 21 after infection." (PMID 22428026, 2012). "Although CD4+CD8+ thymocytes are the main target population in infection, other subsets as DN and SP cells also depleted in infected thymus." (PMID 22518275, 2012). "Consistent with these prior observations the animals used in this study had high viral loads and a rapid and profound depletion of intestinal CD4+ T cells with a nadir at 21d after infection." (PMID 22511950, 2012). "After VK627 and rTsE627K infection, the numbers of CD4+ and CD8+ T cells displayed an identical or lower level compared with mock group from day 1 to 5 p.i., but exhibited a progressive increase in rVK627E and TsE627 groups." (PMID 22719870, 2012). "Considering our previous findings that HIV replicates actively in T-cells with a Th1Th17 polarization profile, these results suggest that HIV-specific CD4+ T-cells in SP subjects are also permissive to infection." (PMID 22470433, 2012). "Most of these models rely on activation steps for not only expanding CD4+T cells but also for infection, as several reports have shown blocks to HIV infection in resting CD4+T cells." (PMID 22911005, 2012). "The three groups were similar with respect to age (p = 0.95), gender (p = 0.72), time with infection (p = 0.064), percentage of patients with viral suppression (p = 0.81), and CD4 T-cell count (p = 0.359)." (PMID 23056229, 2012). "Thirteen patients died due to infections, including sepsis, pneumonia, Fusarium mycosis, and progressive multifocal encephalopathy, which occurred in a patient with low CD4 count at baseline." (PMID 23205258, 2012). "This framework shows that dendritic cells drive the infection in the early stage of an HIV infection when CD4+ T-cell densities are low." (PMID 23202449, 2012). "Human immunodeficiency virus type 1, (HIV-1) infection in T cells requires viral binding to two receptors, CD4+ and a chemokine co-receptor, either CXCR4 or CCR5." (PMID 22448282, 2012). "While the major effect of Vpr seems to be to enhance infection of macrophages there is also evidence Vpr can enhance the infection of activated CD4+ T lymphocytes under some conditions." (PMID 23344558, 2012). "We reasoned that detailed understanding of how LTBI and BCG vaccination shape long-lived memory CD4+ T cell compartments in healthy individuals should provide important insights into the nature of infection- and vaccine-induced immunity." (PMID 22545156, 2012). "Cellular proliferation was also significantly increased during acute phase of infection in both CD4+ and CD8+ populations." (PMID 22905277, 2012). "We performed assays on FACS-sorted resting CD4 T cells obtained from PBMC samples collected over the course of infection, and compared the ratio of WT and EM virus in plasma with that in SIV DNA in resting cells." (PMID 22496643, 2012). "The LLO-reactive CD4 T cell hybridomas also responded to DC infected with live L. monocytogenes at multiplicities of infection (MOI) ranging from 0.1–5." (PMID 22403645, 2012). "The purpose of this study is to use computer simulation of an infection system to evaluate activated healthy CD4+ cell recovery (and thus therapeutic potential) in a hunter virus therapy targeted to both HIV-infected cells and free HIV virions." (PMID 23217087, 2012).
infection (continued). "In vivo analysis of CD4 T cell differentiation during infection has often involved visualization of adoptively transferred TCR transgenic T cells." (PMID 22275869, 2012). "For half of the models (BBH, Eaton, EMOD, Fraser, Goals, Granich, and HIV Portfolio), increasing the percentage of the population with access to treatment reduced the amount of treatment per infection averted, at least at earlier CD4 initiation thresholds." (PMID 22802730, 2012). "In this discussion, our results suggest that the Th2 differentiation of CD4+ T cells occurs during CMt infection to efficiently combat CMt." (PMID 23216686, 2012). "Infection levels of each pseudovirus in the CD4-low cells were then expressed relative to the values obtained in the CD4-high cells." (PMID 22693444, 2012). "Knockdown of p21 in CD4+ T cells relieved a block in proviral transcription following infection of CD4+ T cells from elite controllers and resulted in increased kinase activity of Cdk9 on the RNAP II CTD Ser2 residues." (PMID 24832049, 2012). "Comparing the HH genotype with the combined LL with LH genotypes (LL+LH) confirmed the elevated CD4 cell numbers prior to infection for individuals with the HH genotype (p = 0.007)." (PMID 22412885, 2012). "The results revealed a significant downregulation of cell membrane CD4 in pAd-IDOEGFP infected cells when compared to that of mock-infected cells or infection with empty vector pAd-EGFP." (PMID 23109825, 2012). "Serum levels of IL-21 are significantly reduced in HIV-infected individuals early in infection and positively correlated with CD4+ T cell counts." (PMID 22511950, 2012). "Flow cytometric analyses of immune cell populations indicates an increased percentages of IL-17+ and RORγt+ CD4+ T cells following the infection as well as increased percentages of Th17 cells in spleens of T cell-specific PPARγ null mice." (PMID 23071818, 2012). "These samples were matched for age, CD4 T Lymphocyte count and viral load with R5 samples, again three of which were confirmed as R5 by in vitro infection experiments." (PMID 22493731, 2012). "BrdU administration in vivo showed that CD200R+ CD4 T cells in spleen and lymph node had proliferated upon infection." (PMID 22496920, 2012). "In HIV-infected NSG humanized mice, we observed down-regulation of CD27 expression in CD4+ (from 91.25±1.70% positive before infection to 82.00±2.94% at week 6) and CD8+ T cells (from 91.25±1.89% to 77.50±3.11%)." (PMID 22675567, 2012). "Increased protection correlated with an increased percentage of TB10.4 specific IFNγ/TNFα/IL-2 or TNFα/IL-2 producing CD4 T cells at the site of infection." (PMID 22768165, 2012). "We pretreated cells with either AMD3100 or JWH-133 and then conducted a 3-hour transfer experiment using dye-labeled donor CD4+ T cells infected with the NL-GI virus, the same as was used for cell-free assessment of productive infection." (PMID 22448282, 2012). "No statistical difference was observed in distribution of DR strains by gender, age, infection route, ethnicity, CD4 cell count or HIV-1 subtype." (PMID 23270497, 2012). "A recent study also demonstrated that cell-free HTLV-1 efficiently infects DCs, and the infected DCs promote de novo infection of CD4 T cells." (PMID 23198153, 2012). "Phenotypic assays measure single and multiple rounds of infection in both laboratory immortalized cell lines (e.g., HeLaP4) and primary CD4+ T cells and macrophages." (PMID 22928108, 2012). "A recent study in SIV-infected macaques has shown that depleting CD4+ during PHI worsen the infection." (PMID 23236388, 2012). "CD4+ T cells – the primary cellular target of HIV-1 – are progressively depleted over the course of infection." (PMID 22876188, 2012). "After infection, apoptosis of CD4+ and CD8+ T cells was increased 1.6-fold (p<0.01 vs. PBS-Co) and 1.5-fold (p = 0.01 vs. PBS-Co) in the PBS-treated mice, respectively." (PMID 22815907, 2012).